NCKAP5 (NCK associated protein 5)
Synonyms: NAP5; ERIH1; ERIH2
Tractability: Antibody: the Human Protein Atlas places it where antibodies can reach.
Gene: Protein-coding gene on chromosome 2 (132,671,788 to 133,568,463, reverse strand). Ensembl gene ENSG00000176771.
Subcellular location (Human Protein Atlas): Nucleoli; Cytosol; Golgi apparatus; Plasma membrane
Gene Ontology:
Molecular function: protein binding
Biological process: microtubule bundle formation; microtubule depolymerization
Cellular component: microtubule plus-end
Genetic constraint (gnomAD): Loss-of-function variants: 73 observed, 141.24 expected, observed/expected ratio (o/e) 0.52, 90% interval 0.43 to 0.63. The upper end of that interval is the gene's LOEUF score, 0.63, which puts it in group 2 of 6, group 1 being the genes least tolerant of losing a copy. Missense variants: 2,240 observed, 2,246.1 expected, observed/expected ratio (o/e) 1, 90% interval 0.96 to 1.03. Synonymous variants: 843 observed, 860.74 expected, observed/expected ratio (o/e) 0.98, 90% interval 0.93 to 1.04.
Homologues: Orthologues: chimpanzee NCKAP5 (95% identical), macaque NCKAP5 (90% identical), dog NCKAP5 (76% identical), rabbit NCKAP5 (75% identical), pig NCKAP5 (72% identical), mouse Nckap5 (65% identical), rat Nckap5 (65% identical), guinea pig NCKAP5 (64% identical), Drosophila melanogaster CG42663 (8% identical). Paralogues in human: NCKAP5L (14% identical).
Diseases named in the same sentence as NCKAP5 in open-access papers:
NCKAP5 is named in the same sentence as 22 diseases in open-access papers, as found by Europe PMC text mining. Sharing a sentence is not in itself a finding about the gene and the disease. The quoted sentences say what the papers report.
schizophrenia (4 papers, 2013 to 2020). A major psychotic disorder characterized by abnormalities in the perception or expression of reality. "To date, NCKAP5 has been implicated in GWAS of BD, schizophrenia, hypersomnia, personality traits, and mood states." (PMID 32066727, 2020). "Further meta-analysis of combination of schizophrenia and bipolar disorder confirmed the association between NCKAP5 variants and both schizophrenia and bipolar disorder (Wang, Liu & Aragam, 2010)." (PMID 23646285, 2013).
bipolar disorder (3 papers, 2013 to 2022). A disorder of the brain that causes unusual shifts in mood, energy, activity levels and the ability to carry out day-to-day tasks. "NCKAP5 variants are reportedly strongly associated genes with bipolar disorder, attention deficit hyperactivity disorders, and multiple sclerosis." (PMID 23646285, 2013). "Other regulated genes by Sox13 might be associated to PD syndrome; for example, Nckap5 is considered the most promising candidate for bipolar disorder, and Epb41l2 gene is associated with cognitive impairment in the hippocampus induced by anesthesia." (PMID 36142685, 2022).
multiple sclerosis (2 papers, 2013 to 2026). A progressive autoimmune disorder affecting the central nervous system resulting in demyelination. "Subcluster 2 expressed high levels of white matter associated genes (NRP1, MERTK, and NCKAP5) while subcluster 3 displayed a disease‐associated signature (STARD13, MITF, GPNMB, and DPYD) previously observed in Alzheimer's disease (AD) and Multiple Sclerosis (MS)." (PMID 41283828, 2026).
anxiety disorder (1 paper, 2024). A category of psychiatric disorders which are characterized by anxious feelings or fear often accompanied by physical symptoms associated with anxiety. "Notably, entities such as CAMKMT, NCKAP5, CASC8, and rs56242606 exhibit positive associations with anxiety disorders." (PMID 39165506, 2024). "NCKAP5 may contribute to the pathophysiology of anxiety disorders by affecting synaptic plasticity and neuronal development." (PMID 39165506, 2024).
breast tumors (1 paper, 2012). "In addition, the expression of NCKAP5 and FGF19 is deregulated in specific histopathological types of human breast tumors." (PMID 23131872, 2012).
depression (1 paper, 2019). "A genome-wide association study revealed that a polymorphism near NCKAP5 showed significant link with symptoms of depression in humans." (PMID 31010979, 2019).
ductal carcinoma in situ (1 paper, 2012). "NCKAP5 expression was found in invasive ductal carcinomas (IDC), mixed IDC with ductal carcinoma in situ (DCIS) and invasive lobular carcinoma (ILC) expression patterns." (PMID 23131872, 2012).
mastitis (1 paper, 2019). Inflammation of breast tissue during lactation or postpartum due to an obstructed duct or infection. "In current results, Nckap5 is hypo-methylated in S. aureus mastitis mice." (PMID 31010979, 2019). "In addition, NCK-associated protein 5 (Nckap5) and transposon MTD were identified to be differentially methylated through secondary polymerase chain reaction and sequencing in the mastitis group." (PMID 31010979, 2019). "Our findings revealed hypo-methylation of Nckap5 in S. aureus-induced mastitis mice." (PMID 31010979, 2019). "Subsequently, two differentially methylated genes ( Nckap5 and transposon MTD) in mouse udder tissue were obtained, which may have important roles in the development or resistance of S. aureus mastitis." (PMID 31010979, 2019). "In aggregate, the data obtained in current research and the previously reported studies infer the importance of Nckap5 and transposon MTD as indicators and they might be targets in remedies of mastitis." (PMID 31010979, 2019). "Collectively, our study suggests that the methylation modification in Nckap5 and transposon MTD might be considered as epigenetic markers in resistance to S. aureus-infected mastitis and provided a new insight into S. aureus mastitis research in dairy industry and public health." (PMID 31010979, 2019). "In addition, we suggested that the DNA methylation variation of Nckap5 and transposon MTD might be considered as indicators and methylation markers in a control strategy of S. aureus mastitis, and provided a new insight into S. aureus mastitis research in dairy industry and public health." (PMID 31010979, 2019).
prostate carcinoma (1 paper, 2017). A carcinoma that arises from epithelial cells of the prostate gland. "NCKAP5 is a gene in the large region of inversion at 2q21.3-q22.1 and has been observed to be rearranged in prostate cancer by FISH." (PMID 28945760, 2017).
sarcoma (1 paper, 2024). A usually aggressive malignant neoplasm of the soft tissue or bone. "Interestingly, cytoskeleton proteins, including RASA1, RASAL2, NCKAP5, MACF1 and ARHGAP24, were reduced following differentiation, indicating that the sarcoma microenvironment induces resident‐like myeloid cell transfer." (PMID 39658531, 2024).
tumor (2 papers, 2012 to 2024). "Multivariate Cox regression analysis identified SNPs in 8 genes (Stx6, Ramp1, Traf3ip1, Nckap5, Pfkfb2, Trmt1l, Rprd1b, and Rer1) that were independently associated with age of tumour onset." (PMID 39067134, 2024). "Only two susceptibility genes (Nckap5 and Ptprt) overlap among all tumour phenotypes (onset, multiplicity, and metastasis)." (PMID 39067134, 2024). "We pooled all 20 genes (Stx6, Ramp1, Traf3ip1, Nckap5, Pfkfb2, Trmt1l, Rprd1b, Rer1, Sepsecs, Rhobtb1, Tsen15, Abcc3, Arid5b, Tnr, Dock2, Tti1, Fam81a, Oxr1, Plxna2 and Tbc1d31) together as the mouse tumour susceptibility gene signature (mTSGS)." (PMID 39067134, 2024). "The transcriptional orientation of the MMTV genome relative to the transcriptional orientation of the gene in which it integrated, was determined for four genes (Usp31, Nckap5, Cadm2 and Notch4) for which there was available tumor RNA." (PMID 23131872, 2012). "Multivariate analyses flagged SNPs in 20 genes (Stx6, Ramp1, Traf3ip1, Nckap5, Pfkfb2, Trmt1l, Rprd1b, Rer1, Sepsecs, Rhobtb1, Tsen15, Abcc3, Arid5b, Tnr, Dock2, Tti1, Fam81a, Oxr1, Plxna2, and Tbc1d31) independently tied to various tumour characteristics, designated as a mTSGS." (PMID 39067134, 2024).
psychiatric disorder (1 paper, 2020). A disorder characterized by behavioral and/or psychological abnormalities, often accompanied by physical symptoms. "This cumulative evidence for an association with neuropsychiatric disease and other phenotypes, combined with the present WES finding, suggests that NCKAP5 may contribute to the development and maintenance of a broad spectrum of psychiatric disorders, including BD." (PMID 32066727, 2020).
NCKAP5 also shares sentences with these, for which no sentence is quoted: Alzheimer disease (1 paper); attention deficit-hyperactivity disorder (1); autism (1); cancer (1); Cognitive impairment (1); dwarfism (1); gastric cancer (1); hypersomnia (1); invasive ductal carcinomas (1); invasive lobular carcinoma (1).